IGF2 (insulin like growth factor 2)
Diseases named in the same sentence as IGF2 in open-access papers (continued):
Sharing a sentence is not in itself a finding about the gene and the disease.
endometrial cancer (13 papers, 2006 to 2025). Primary or metastatic malignant neoplasm involving the endometrium (mucous membrane that lines the endometrial cavity). "Hence, these studies suggest that over-expression of the IGF1R and IGF2 genes is associated with poor outcome in endometrial cancer." (PMID 24904527, 2014). "Previous studies have demonstrated that insulin-like growth factor 1 (IGF-1) and IGF-2 promote cell proliferation in endometrial cancer cells, while metformin reverses this effect and inhibits cell proliferation." (PMID 25289085, 2014). "The correlation between IGF1R and IGF2 expression levels with endometrial cancer stage was investigated in a study that included specimens from 59 endometrial adenocarcinoma cases, 10 endometrial hyperplasia cases, and 7 normal controls." (PMID 24904527, 2014). "IGF1 and IGF2 do not show significant associations with the risk of endometrial cancer in the entire population." (PMID 38339282, 2024). "While the increase of IGF2 in Herceptin resistant cells was attributed to the decrease of miR-193a-5p via inactivation of FOXO3a, this miRNA was shown to be involved in tumorigenesis of endometrial carcinoma through directly targeting YY143." (PMID 33976188, 2021). "Interestingly, compared to control subjects where IGF levels decreased after menopause, post-menopausal women in the study group showed elevated IGF1 and IGF2 levels, suggesting a potential influence of endometrial cancer on the IGF system, particularly after menopause." (PMID 38339282, 2024). "So far, IGF2 has not been adequately studied in endometrial cancer, and more attention needs to be paid to its role in endometrial cancer for better therapeutic interventions." (PMID 37393293, 2023). "This study examined a set of six markers, namely, adiponectin, leptin, IL6, TNFα, IGF1, and IGF2 and compared them between fifty age-matched endometrial cancer patients (study group) and non-cancer patients with benign gynaecological conditions (control group)." (PMID 38339282, 2024). "Genetic variation in IGF2 and IFGBP3 may influence the risk of endometrial cancer in Caucasians, but IGFBP1 SNP rs4619 showed no such association." (PMID 27144430, 2016).
esophageal cancer (13 papers, 2006 to 2025). A primary or metastatic malignant neoplasm involving the esophagus. "Increased levels of IGF-1 and IGF-2 are associated with many cancers, including esophageal cancer." (PMID 32041673, 2020). "For instance, in esophageal cancer models, IGF2 secreted by Id1-overexpressing cells induced CAFs to produce and secrete vascular endothelial growth factor (VEGF) by inhibiting miR-29c." (PMID 36672737, 2023). "Blockade of IGF2 by a neutralizing antibody inhibited stem-like cell features and suppressed the growth of esophageal cancer xenografts." (PMID 36672737, 2023). "In esophageal cancer cells, IGF2 was crucial in inducing and maintaining stemness through the PI3K/Akt/MiR-377/CD133 pathway." (PMID 36672737, 2023). "In addition, Id1-overexpressing esophageal cancer xenografts were characterized by IGF2-dependent metastatic spread." (PMID 36672737, 2023). "Cancers of the oesophagus, mouth and pharynx were significantly associated with lower levels of IGF-1 and cancer of the lymphoma was significantly associated with lower levels of IGF-2." (PMID 16804529, 2006). "Similarly, IGF2 expression was associated with Id1 and activated AKT in esophageal cancer tissues." (PMID 36672737, 2023). "Studies have shown that miR-454-3p overexpression can inhibit the expression of insulin-like growth factor 2 mRNA-binding protein 1 (IGF2BP1) at the protein and mRNA expression levels and thus inhibit the occurrence and development of esophageal cancer." (PMID 34234806, 2021).
melanoma (13 papers, 2013 to 2025). A malignant, usually aggressive tumor composed of atypical, neoplastic melanocytes. "Inoculation of EO771 tumor cells, MC38 tumor cells, and B16-F10 melanoma cells into Igf2-cKO mice revealed increased T cell infiltration and retarded tumor burden compared with that seen in WT mice, similar to Igf2–/– mice." (PMID 39545420, 2024). "Melanoma model in zebrafish has confirmed that THOR-IGF2BP1 interaction promotes melanoma development and progression by stabilizing several oncogenes such as IGF2 and CD44." (PMID 34638331, 2021). "IGF1 & IGF2 and their cognate receptors are important regulators of multiple human cancers, including melanoma." (PMID 28223541, 2017). "When compared to malignant melanoma, NCH showed relative overexpression of IGF2 and H19, suggesting the abnormal gene imprinting and IGF2 overexpression are likely to play crucial rules in the development of NCH." (PMID 40265343, 2025). "In patients with melanoma undergoing anti–PD-1 therapy, elevated levels of IGF2 mRNA were observed in pretreatment tumors from nonresponders relative to levels in responders." (PMID 39545420, 2024). "Additionally, analysis of another scRNA-Seq dataset obtained from the Gene Expression Omnibus (GEO) database revealed heightened levels of IGF2 in CAFs, with this trend further exacerbated in ICB-resistant melanoma compared with ICB-untreated melanoma." (PMID 39545420, 2024). "This might partly explain the resistance of melanoma cells to IGFs, because IGF2R directs IGF2 to lysosomes to attenuate signaling." (PMID 32534480, 2020). "We did not detect any endogenous insulin or IGF2 RNA or protein levels in any of the four melanoma cells tested, but our RT-qPCR studies revealed presence of IGF1 RNA that is supported by recent reports." (PMID 28223541, 2017). "However, the role of endocrine or paracrine IGF1, insulin or IGF2 in an entire organism might reveal additional effects and provide for a holistic analysis of this aspect of IGF regulation in melanoma." (PMID 28223541, 2017). "We detected no IGF2 or insulin RNA expression in the melanoma cell lines." (PMID 28223541, 2017).
meningioma (12 papers, 2009 to 2024). A generally slow growing tumor attached to the dura mater. "Since miR-483-5p, miR-675-5p, and IGF-2 mRNA appeared to be closely linked and upregulated in meningioma samples, we tested additional meningioma tumor samples for IGF-2 protein expression." (PMID 36809604, 2023). "Meningioma tumor samples showed high, grade-dependent expression of miR-483-5p, associated with high mRNA and protein expression of its host gene IGF-2." (PMID 36809604, 2023). "Anti-IGF-2 neutralizing antibodies are also effective in reducing the proliferation of meningioma cells." (PMID 38577017, 2024). "This study highlights the critical dependence of meningioma cell growth on the autocrine miR-483/IGF-2 stimulation pathway." (PMID 38577017, 2024). "Another study found high and grade-dependent expression of miR-483–5p in meningioma tumor samples, which correlated with increased mRNA and protein levels of its host gene IGF-2." (PMID 38577017, 2024). "The results showed that IGF-2 autocrine feedback is critical for the survival and growth of meningioma tumor cells." (PMID 38577017, 2024). "Western blot analysis showed robust Akt phosphorylation after IGF-2 exposure, suggesting that IGF-2 is capable of activating a mitogenic pathway and thus stimulating meningioma growth." (PMID 36809604, 2023). "To investigate the function of miR-483-5p/IGF-2 circuit in meningioma, we first assessed effects of miR-483-5p modulation on meningioma growth." (PMID 36809604, 2023). "In contrast, western blot analysis of fresh-frozen tumor samples reproducibly showed high IGF-2 protein expression in all meningiomas studied." (PMID 36809604, 2023). "Established meningioma cell lines C157-MN and F5 also express high level IGF-2 although lower than the tumor samples." (PMID 36809604, 2023). "Inhibition of the miR-483/IGF-2 pathway with miR-483 oligonucleotide inhibitor, anti-IGF-2 neutralizing antibodies, and IGF1R small molecule tyrosine kinase inhibitors caused rapid loss of viability of cultured meningioma tumor-derived cells." (PMID 36809604, 2023). "Meningioma cell growth is critically dependent on autocrine miR-483/IGF-2 stimulation and the IGF-2 pathway provides a feasible meningioma treatment target." (PMID 36809604, 2023). "Despite the lack of efficacy observed in high grade cancers, our data suggests that IGF1R blockade has promise in meningioma treatment, given meningioma’s apparent high dependence on the IGF-2 pathway." (PMID 36809604, 2023). "Adding two distinct anti-IGF-2 neutralizing antibodies to the culture media resulted in reduced cell growth in diverse primary meningioma cultures." (PMID 36809604, 2023). "Meningioma cell growth appears to be critically dependent on autocrine IGF-2 stimulation and the IGF-2 pathway provides a possible meningioma treatment target." (PMID 36809604, 2023). "Here, using primary meningioma cells, we demonstrate that inhibition of either miR-483-5p or IGF-2 reduce meningioma growth offering a new therapeutic strategy for these highly prevalent brain tumors." (PMID 36809604, 2023). "Analysis of an additional public dataset, with 96 meningioma samples and 13 normal meninx controls confirmed that IGF-2 mRNA is upregulated in meningioma compared to controls." (PMID 36809604, 2023). "IGF-2 is a powerful mitogen for meningioma cells as demonstrated by Akt phosphorylation following addition of recombinant IGF-2." (PMID 36809604, 2023). "Notably, the IGF-2 pathway is emerging as a promising and feasible therapeutic target for the treatment of meningioma." (PMID 38577017, 2024). "The immortalized arachnoid (non-meningioma) cell line AC007T showed low level of IGF-2 expression." (PMID 36809604, 2023). "Similarly, inhibition of this pathway with anti-IGF-2 neutralizing antibodies reduced meningioma cell proliferation." (PMID 36809604, 2023).
meningioma (continued). "Although IGF-2 upregulation has been previously reported in meningiomas, along with H19-IGF2 locus imprinting and overexpression of miR-483-5p, comprehensive IGF-2 expression analysis has been hampered by technical difficulties using formaldehyde-fixed paraffin-embedded samples." (PMID 36809604, 2023). "Western blot analysis revealed that most meningiomas expressed high levels of IGF-2." (PMID 36809604, 2023). "Small molecule tyrosine kinase inhibitor blockade of the IGF-2 receptor (IGF1R) resulted in rapid loss of viability of cultured meningioma tumor-derived cells, suggesting that autocrine IGF-2 feedback is obligatory for meningioma tumor cell survival and growth." (PMID 36809604, 2023). "Inhibition of miR-483–5p, anti-IGF-2 neutralizing antibodies, and small molecule tyrosine kinase inhibitors targeting IGF1R have demonstrated efficacy in limiting meningioma cell proliferation in vitro." (PMID 38577017, 2024). "miRNA modulation, anti-IGF-2 neutralizing antibodies, and inhibitors against IGF1R were evaluated in a tumor-derived primary cultures of meningioma cells." (PMID 36809604, 2023). "Meningioma tumor cells also express a high level of IGF1R, the main receptor for IGF-2." (PMID 36809604, 2023). "A study of signaling pathways and miRNA in 16 grade 1 and 16 grade 2 meningioma samples found a similar pattern of miRNA expression including miR-483-5p upregulation, however, the functional activity of miR-483-5p and IGF-2 was not explored by these authors." (PMID 36809604, 2023). "IGF-2-mediated Akt phosphorylation was also strongly blocked by GSK1838705A, ceritinib and linsitinib suggesting that the mechanism by which these drugs inhibit meningioma cell growth is mainly via IGF1R blockade." (PMID 36809604, 2023). "Finally, laboratory studies have confirmed that IGF1, IGF2, and IGF1R genes are overexpressed in meningioma." (PMID 24587258, 2014). "Whereas inhibition of either miR-483 or IGF-2 may provide therapeutic strategy for meningioma, miRNA-targeting with oligonucleotide drugs have not yet been clinically established for brain tumors." (PMID 36809604, 2023).
thyroid cancer (12 papers, 2006 to 2022). "By the way, the over-activation of IR-A/IGF-2 loop was also reported to be associated with thyroid cancer stem-like features and refractoriness to some targeted therapies." (PMID 33173015, 2020). "In human thyroid cancer, cells cultured as thyrospheres and acquiring stem-like features, have an up-regulation of the IGF-2/IR-A loop, strongly associated with tumor aggressiveness and loss of differentiation." (PMID 30453495, 2018). "Overexpression of IGF-1, IGF-1R, IGF-2 and insulin receptor (IR) can be seen in the early stage of thyroid cancer." (PMID 35711846, 2022). "An increased IR-A expression and IGF-2 production was observed in primary cultures of thyroid cancer cells and in thyroid cancer specimens compared to normal thyroid cells." (PMID 30453495, 2018). "In stem/progenitor thyroid cancer cells, the IGF-2/IR-A loop was up-regulated." (PMID 30453495, 2018). "In thyroid cancer cells, over expression of the IGF2BP3/IGF2 axis correlates with enhanced activation of the Akt and ERK pathways, increased cell proliferation and sensitivity to the dual inhibitor OSI-906." (PMID 33673232, 2021). "Overexpression of IGF2BP3 mRNA and protein increases IGF2 translation and IGF1 receptor (IGF1R) signaling through PI3K and MAPK cascade reaction and promotes proliferation, invasion, and transformation of thyroid cancer cells." (PMID 33796449, 2021). "In undifferentiated thyroid cancer cells, DDR1 downregulation inhibits the IGF2/IR-A signaling pathway and increases the expression of differentiation markers, such as TSH and TPO, and decrease of EMT and stemness markers, like Nanog, ABCG2 and vimentin." (PMID 33673232, 2021). "We detect a number of recurrent fusions, such as those involving ANO3, RGS9, FUT5, CHI3L1, OR1D4, and LIPG in breast; IGF2 in colon; ETV1 in prostate; and IGF2BP3 and SIX2 in thyroid cancers." (PMID 32631391, 2020). "Similarly, IGF2BP3 binds the IGF2 3′-UTR, thus promoting its translation, increasing activation of IGF signaling and cell proliferation in leukemia, thyroid cancer and glioma." (PMID 33673232, 2021). "Interestingly, the IGF2 mRNA-binding protein 1 (IGF2BP1) was recently shown to be upregulated in the majority of ATCs, while absent in poorly differentiated and well-differentiated thyroid carcinoma." (PMID 34944959, 2021).
autism (11 papers, 2016 to 2024). Persistent deficits in social interaction and communication and interaction as well as a markedly restricted repertoire of activity and interest as well as repetitive patterns of behavior. "IGF2 encodes insulin-like growth factor II, which is a cognitive enhancer and can reverse autism-like phenotypes in mice." (PMID 33160303, 2020). "In autistic disorders, Igf2 stimulation leads to a reversal of the clinical signs of autism (restoration of social behavior, abolition of repetitive behaviors, etc.)." (PMID 35741015, 2022). "Similar results in other mouse autism models indicate IGF2 ameliorates a number of cognitive and social interaction impairments." (PMID 33608547, 2021). "IGF-2 treatment improved cognitive/executive functions by targeting the AMPK-mTOR-S6K pathway in a mouse model of Autism." (PMID 32191705, 2020). "Recent studies suggest that IGF1 analogs or IGF2 could help alleviate social and behavioral deficits in autism, indicating a potential link between IGF signaling disruptions and autism." (PMID 39376742, 2024). "Interestingly, Igf2 protein can reverse the core autism symptoms in the BTBR mouse model, by reducing the overactivation of mTOR pathway." (PMID 33049717, 2020). "IGF2 is a neurotrophic factor that plays a crucial role in hypoxic–ischemic brain injury, ALS, autism, AD and PD." (PMID 37668106, 2023).
colorectal tumors (11 papers, 2005 to 2025). "The autocrine/paracrine effect of IGF2 mainly involves polypeptides produced by extrahepatic tissues, including colorectal tumor cells and CRC tumor stromal cells (cancer-associated fibroblasts)." (PMID 34422629, 2021). "Autocrine/paracrine effects of IGF2 mainly concern the polypeptide produced in extra-hepatic tissues, including colorectal tumor cells and CRC tumor stroma (cancer-associated fibroblasts (CAFs))." (PMID 31623387, 2019). "In humans IGF-II was suggested to play a role in development of CRC, as substantiated by findings showing that IGF-II is overexpressed in about 44% of all colorectal tumors due to a loss of imprinting (LOI) in the IGF2 gene." (PMID 17118177, 2006). "Loss of imprinting (LOI) of the insulin-like growth factor 2 (IGF2) gene is an epigenetic abnormality observed in human colorectal neoplasms." (PMID 23171475, 2012). "Several lines of evidence suggest that IGF-2 plays an important role in the progression of colorectal tumours." (PMID 15785755, 2005). "The role of IGF2 in CRC etiology and pathogenesis is indicated by epidemiological data and studies on tissue IGF2 expression in colorectal tumors." (PMID 31623387, 2019).
Glucose intolerance (11 papers, 2013 to 2024). Glucose intolerance (GI) can be defined as dysglycemia that comprises both prediabetes and diabetes. "Thus, our results show that mesenchyme-specific Igf2 deletion results in postnatal whole-body growth restriction and maternal glucose intolerance during pregnancy." (PMID 33057429, 2020). "Our postnatal studies provide proof of principle that lack of mesenchyme-derived IGF2 has physiological consequences related to whole-body growth (first observable around weaning) and glucose intolerance during pregnancy." (PMID 33057429, 2020).
Infertility (11 papers, 2013 to 2024). "KCNQ1 and IGF-2 have also been documented to be associated with serious sperm DNA damage in infertile males." (PMID 36357889, 2022). "Loss of methylation at DMRs of both IGF2 and H19 at variable CpG positions is correlated with an increase in abnormal sperm and infertility in men." (PMID 36061209, 2022). "Recently, seminal plasma IGF-I was found to be associated with sperm motility in infertile patients, and methylation levels of IGF-2 in spermatozoa from infertile men may be associated with sperm DNA fragmentation." (PMID 36381356, 2022). "Moreover, abnormal methylation of the imprinted genes IGF2 and KCNQ1 at the spermatozoon level has recently been reported in infertile patients, in association with an increased sperm DNA fragmentation." (PMID 32138324, 2020). "The disappearance of the relationship between IGF2 expression and IGF2AS and H19 methylations in the infertile group provides new information regarding the disruption of epigenetic programming during spermatogenesis." (PMID 39017772, 2024). "Further supporting this notion was the finding that the IGF2 DMR is also highly methylated in the spermatozoa, in agreement with the methylation findings in sperm for this region from another study of infertility." (PMID 23745176, 2013). "Aberrant methylation patterns at DMRs of genes such as IGF2, H19, and GTL2 in Y chromosome-containing prospermatagonia during spermatogenesis have been explored as specific epigenetic alterations to maternally imprinted genes of infertile men." (PMID 36061209, 2022). "However, IGF2 expression was significantly upregulated in fertile individuals whose 2nd CpG of IGF2AS was hypermethylated, unlike in the infertile group." (PMID 39017772, 2024). "Additionally, IGF2 mRNA expression in the fertile group was significantly correlated with IGF2AS methylation at the 2nd CpG (r = 0.388), while this correlation was not present in the infertile groups." (PMID 39017772, 2024).